KRTAP8-1 (keratin associated protein 8-1)
Description:
In the hair cortex, hair keratin intermediate filaments are embedded in an interfilamentous matrix, consisting of hair keratin-associated proteins (KRTAP), which are essential for the formation of a rigid and resistant hair shaft through their extensive disulfide bond cross-linking with abundant cysteine residues of hair keratins. The matrix proteins include the high-sulfur and high-glycine-tyrosine keratins.
Synonyms: KAP8.1
Tractability: No criterion of Open Targets' tractability assessment is met for any kind of drug.
Gene: Protein-coding gene on chromosome 21 (30,812,697 to 30,813,274, reverse strand). Ensembl gene ENSG00000183640.
Pathways (Reactome):
Developmental Biology: Keratinization
Gene Ontology:
Molecular function: protein binding
Cellular component: cytosol
Genetic constraint (gnomAD): Loss-of-function variants: 4 observed, 5.35 expected, observed/expected ratio (o/e) 0.75, 90% interval 0.37 to 1.62. That is too few expected variants to judge how well the gene tolerates losing a copy. Missense variants: 79 observed, 84.29 expected, observed/expected ratio (o/e) 0.94, 90% interval 0.78 to 1.13. Synonymous variants: 35 observed, 37.05 expected, observed/expected ratio (o/e) 0.94, 90% interval 0.72 to 1.25.
Homologues: Orthologues: chimpanzee KRTAP8-1 (98% identical), dog KRTAP8-1 (90% identical), guinea pig KRTAP8-1 (86% identical), rat Krtap8-1 (84% identical), mouse Krtap8-1 (83% identical), pig KRTAP8-1 (79% identical).
Diseases named in the same sentence as KRTAP8-1 in open-access papers:
KRTAP8-1 is named in the same sentence as 5 diseases in open-access papers, as found by Europe PMC text mining. Sharing a sentence is not in itself a finding about the gene and the disease. The quoted sentences say what the papers report.
lung carcinoma (1 paper, 2019). "For lung cancer, it was shown that the methylation levels of HOXA9, KRTAP8-1, CCND1, and TULP2 have great potential for the early recognition of LUAD in the undetermined lung nodules." (PMID 31850197, 2019).
tumor (1 paper, 2019). "In this study, we systematically analyzed the DNA methylation data of LUAD and found that the hypermethylation of HOXA9 and the hypomethylation of KRTAP8-1, CCND1, and TULP2 were observed in LUAD tumor samples." (PMID 31850197, 2019). "In these LUAD patients, the methylation of HOXA9 was significantly upregulated, whereas the methylation of KRTAP8-1, CCND1, and TULP2 were downregulated obviously in tumor samples compared with adjacent tissues." (PMID 31850197, 2019). "The results further confirmed that the hypermethylation of HOXA9 and the hypomethylation of KRTAP8-1, CCND1, and TULP2 were observed in LUAD tumor samples." (PMID 31850197, 2019).
KRTAP8-1 also shares sentences with these, for which no sentence is quoted: cancer (2 papers); endometrial cancer (1); lung adenocarcinoma (1).